INS (insulin)
Diseases named in the same sentence as INS in open-access papers (continued):
Sharing a sentence is not in itself a finding about the gene and the disease.
diabetes (continued). "One multi-center cross-sectional survey of outpatients in Chinese hospitals showed that approximately 65.6% of patients with diabetes used premixed insulin." (PMID 38027146, 2023). "This study demonstrates the potential application of glucose-responsive SF MNs in treating diabetes mellitus through transdermal insulin uptake." (PMID 36810381, 2023). "The values probably reflect a practical coding problem due to the confusion between the concept of "insulin-dependent diabetes" (T89 or type 1 diabetes) and "insulin-treated diabetes" (type 2 diabetes, correctly coded as T90)." (PMID 37061669, 2023). "Participants were at stage 1 or 2 of diabetes, with a fasting blood glucose level of 126 mg/dL, the consumption hypoglycemic medication or insulin, and a proteinuria level of 300 mg/dL." (PMID 37049495, 2023). "Patients in subgroup analyses were categorized based on age, sex, diabetes, smoking, dialysis method, initial presentation, insulin therapy, and PCI intervention (with the TyG index considered as a continuous factor)." (PMID 37891651, 2023). "A total of 47 subjects with insulin-treated diabetes were included, with 32 female participants (68%) and a mean age of 77.72 ± 5.08 years." (PMID 37372168, 2023). "Type 1 diabetes mellitus (T1DM) is an autoimmune disease in which the immune system destroys insulin-producing β cells." (PMID 36942499, 2023). "Model organisms have provided insights into insulin biology and diabetes, with multiple reviews published on this topic." (PMID 36830626, 2023). "Diabetes mellitus is a group of metabolic disorders characterized by an inability of the body to produce or properly respond to insulin, resulting in poor preservation of favorable blood glucose levels and thereby hyperglycemia." (PMID 36715774, 2023). "In the current work, we report that insulin granule trafficking from the Golgi is also impaired in rodent diabetes models and coincides with morphological alterations to Golgi structure." (PMID 36997560, 2023). "Increased production of inflammatory cytokines thus contributes to insulin resistance and the destruction of pancreatic beta cells, which significantly facilitates the onset of diabetes complications." (PMID 36832168, 2023). "Amyloid-β peptide, hyperphosphorylation peptide, hyperphosphorylation of tau, and insulin abnormality are common pathological mediators and processes shared between Alzheimer’s disease (AD) and diabetes." (PMID 38002034, 2023). "This review sought to collate and discuss published data on the cellular and molecular effects of medicinal plants and phytochemicals on insulin signaling pathways to better understand the current trend in using plant products in the management of diabetes." (PMID 36627919, 2023). "It reduces lipogenesis, increases lipolysis and decreases glucose and insulin levels, improving insulin sensitivity and glycemic control in patients with type 2 diabetes mellitus and gonadal function in women with PCOS." (PMID 37960300, 2023). "Analyses reflected that the groups were similar at baseline assessment in terms of demographics (e.g., race, age), A1c, insulin management, and diabetes-related events (p values = 0.086 to >0.900)." (PMID 40303275, 2023). "Type 2 diabetes mellitus (T2DM) is a chronic metabolic disorder characterized by elevated levels of blood glucose due to inadequate insulin secretion or impaired insulin action." (PMID 37370981, 2023). "Diabetes is a metabolic syndrome characterized by a hyperglycemic state due to decreased insulin secretion, defective insulin activity, or both, and it is considered a chronic global epidemic disease." (PMID 37237697, 2023). "Type 2 diabetes mellitus (T2DM) is characterized by hyperglycemia and is caused by a combination of deficient insulin secretion, inadequate insulin resistance, and misleading glucagon secretion." (PMID 37998038, 2023). "Pancreas transplant remains the only realistic, long-term insulin-independent treatment for diabetes." (PMID 38370534, 2023).
diabetes (continued). "Type 2 diabetes mellitus (T2DM) is the most common form of the disease, which is characterized by relative insulin secretion deficiency and insulin resistance in target organs." (PMID 37111272, 2023). "According to this study, newly diagnosed individuals with diabetes who underwent regular insulin through subcutaneous infusions for two to three weeks experienced glycemic control and β-cell recovery." (PMID 38094528, 2023). "Another study on healthcare inequalities in diabetes confirms the inability to access diabetes management technologies, with a tenfold difference in insulin pump use by type 1 diabetes patients across specialist centers in the UK." (PMID 36650506, 2023). "Type 2 diabetes mellitus is a metabolic disorder characterized by high blood sugar levels resulting from insulin resistance and insufficient insulin production." (PMID 37686346, 2023). "Inflammatory factors, in addition to OS, play a significant role in the development of diabetes by promoting insulin resistance through the alteration of β-cell function and interference with insulin signaling." (PMID 37383391, 2023). "It was observed that the practice of insulin injections was significantly influenced by patient characteristics such age, education level, occupation, the type of diabetes, and the duration of the disease." (PMID 37143082, 2023). "The mRNA expression levels of insulin signaling-related factors such as Ir, Irs1, Akt, and Glut4 declined in adipose tissues in the case of type 2 diabetes mellitus." (PMID 36902049, 2023). "Patients with diabetes who utilize insulin therapy are constantly in contact with medical sharps, including lancets, pen needles, and syringes." (PMID 38099003, 2023). "Insulin-resistant offspring with a family history of diabetes mellitus tend to generate a lower maximal oxygen (O2) consumption because of mitochondrial dysfunction." (PMID 37255932, 2023). "Diabetes mellitus is one of the most common metabolic disorders that occurs when the body is unable to properly manage insulin secretion, insulin action, or both, and is characterized by chronic hyperglycemia." (PMID 37151681, 2023). "Studies have shown that TUDCA and 4-PBA can enhance the effect of insulin and reduce blood sugar levels by regulating endoplasmic reticulum stress, and have potential in the treatment of diabetes." (PMID 35303254, 2023). "People with diabetes usually exhibit four metabolic abnormalities: abnormal insulin action, insulin secretion dysfunction, increased endogenous glucose output, and obesity." (PMID 37108143, 2023). "Multiple linear regression analysis was performed to predict the influence of age, duration of diabetes, race, insurance status, and insulin administration on glycemic outcomes." (PMID 40303248, 2023). "MNT can achieve painless drug delivery, and encapsulating insulin into MN to achieve its effective delivery can play a role in the treatment of diabetes." (PMID 37223469, 2023). "Hyperglycemia is the most prevalent symptom of diabetes, which results in a decrease in insulin production in type 1 diabetes or full resistance or poor insulin secretion in type 2 diabetes." (PMID 38001980, 2023). "Three key targets were identified, namely, anticoagulants, insulin, and oral diabetes agents, and the basis for initiatives such as surveillance and prevention." (PMID 37940971, 2023). "The mean age of the participants was 70.4 years, 51% were women, and all were white; the mean diabetes duration was 17.4 years and the insulin treatment duration was 7.6 years." (PMID 36882852, 2023). "Diabetes mellitus is a chronic, irreversible condition characterized by dysregulated insulin response or synthesis in the body." (PMID 38201117, 2023). "Two major processes involved in diabetes mellitus are a deformed pancreas with altered insulin-secreting cell development and/or survival or faulty functioning of the existing pancreatic beta cell." (PMID 37443665, 2023).
diabetes (continued). "Diabetes mellitus is a disease characterized by a high blood glucose concentration due to insufficient insulin secretion or failure of the pancreas to function normally." (PMID 37463984, 2023). "Women with PCOS should take precautions for the development of type 2 diabetes mellitus since this condition is indicated by raised insulin levels on a two-hour 75-g glucose tolerance test (DM)." (PMID 36751233, 2023). "Currently, the most common treatments of diabetes are still oral hypoglycemic drugs and insulin therapy." (PMID 37763199, 2023). "Women with recurrent GDM revealed a higher prevalence of a positive family history of diabetes (OR 4.3 [95% CI 1.2–15.4], p = 0.016) and needed more frequently an insulin treatment (OR 2.3 [95% CI 1.1–4.6], p = 0.023)." (PMID 36595021, 2023). "The ability of PPAR to promote fatty acid and glucose oxidation and insulin sensitization has also led to the use of the therapeutic agonists, thiazolidinediones in the management of patients with type 2 diabetes mellitus." (PMID 36326284, 2023). "Recognition of the mechanisms responsible for the regulation of insulin secretion and the maintenance of pancreatic β-cell function in diabetes offers hope for the development of effective therapies." (PMID 37195917, 2023). "As lowering blood glucose is the most urgent goal for patients with diabetes, potential adverse effects of long-term insulin administration or hyperinsulinemia are generally ignored." (PMID 37779149, 2023). "Omentin is a novel adipokine with insulin-sensitizing effects and is especially produced by visceral adipose tissue, where circulating levels are decreased in insulin-resistant conditions, such as obesity and diabetes." (PMID 37895024, 2023). "Out of the total 2,378,452 patients with diabetes taking insulin, 5987 patients have a DD diagnosis, resulting in a prevalence of 0.052%." (PMID 37443309, 2023). "Klinischen Studien beschreiben für Menschen mit Typ 1 und Typ 2 Diabetes eine stärkere Reduktion des postprandialen Glukosespitzenwertes unter Fast-acting insulin aspart im Vergleich zu Insulin Aspart." (PMID 37101030, 2023). "The purpose of this study is to analyze the BIs of wearable insulin biosensors among diabetes patients, and the factors that drive or hinder their adoption." (PMID 38239544, 2023). "Reduce blood glucose and insulin levels in type 2 Diabetes mellitus patients Cicero and Baggioni (2016)." (PMID 37790705, 2023). "These intervention determine a dramatically improvement in glycemic control with a reduction in hypoglycemic medication and insulin requirements, leading to remission of diabetes in up to 60-80% of cases in the short term." (PMID 37077356, 2023). "In fact, markers of diabetes, such as fasting blood glucose and HbA1 concentrations, were much less pronounced in Gunn rats with the preservation of insulin secretion by the pancreatic islets of these hyperbilirubinemic animals." (PMID 37445792, 2023). "It is important to take note that enhanced insulin secretion or improved insulin sensitivity is crucial in managing diabetes." (PMID 37959677, 2023). "Diabetes is a long-term condition marked by the body’s incapability to adequately generate or utilize insulin, leading to increased glucose levels in the bloodstream." (PMID 37927470, 2023). "Prices for diabetes medications can vary considerably and the greatest degree of price variation occurs in non-insulin generic therapies." (PMID 38060500, 2023). "Nonetheless, impairment of glucose-stimulated insulin action due to inflammation and oxidative stress can lead to insulin resistance and β-cell dysfunction, subsequently leading to the pathogenesis of type 2 diabetes mellitus." (PMID 37299466, 2023). "Current diabetes medications utilize the insulin and oral hypoglycemic effects within M. charantia to control T2DM and other metabolic conditions." (PMID 36902074, 2023).
diabetes (continued). "Healthcare providers must ensure that psychological resistance to initiating insulin is adequately addressed, and effectively train the persons with diabetes to correctly follow their prescriptions." (PMID 38076524, 2023). "Robertson reported that diabetes mellitus comprises a group of chronic diseases characterized by hyperglycemia or diminished insulin secretion or both." (PMID 35237941, 2023). "In 2001, PEEA was also the culprit allergen in ACD in a 38-year-old woman with diabetes treated with an insulin pump." (PMID 37445875, 2023). "Pancreatic β cells synthetize, store and release insulin to maintain glucose homeostasis and its disfunction leads to IR and ultimately to diabetes." (PMID 37298967, 2023). "For example, it has been reported that the impairment of circadian rhythms leads to the development of diabetes via inducing abnormal insulin secretion, decreasing the insulin sensitivity, and exacerbating the inflammation." (PMID 36838862, 2023). "Diabetes mellitus (DM) is a metabolic disorder characterized by persistent hyperglycemia triggered by the pancreas’ inability to make enough insulin (type 1 DM) or the body's inability to efficiently utilize the insulin it produces (type 2 DM) or both." (PMID 37292102, 2023). "Curcumin alleviated compensatory Nrf2 pathway activation by directly reducing free radicals when combined with insulin, and it better maintained Nrf2 pathway homeostasis compared to insulin alone in the early stages of diabetes." (PMID 36670985, 2023). "Type 1 diabetes mellitus (T1DM) is an autoimmune disorder resulting from the immune-mediated destruction of insulin-producing pancreatic beta cells leading to an absolute deficiency of insulin." (PMID 37779730, 2023). "While an appropriate level of ROS can promote insulin secretion, excessive ROS may trigger a strong oxidative stress response, downregulate insulin gene expression, and directly damage β cells, ultimately leading to the development of diabetes and its associated complications." (PMID 37371975, 2023). "The important role of IPF/PDX1 in diabetes has been shown in a mice model in which targeted disruption of the IPF1/PDX1 gene leads to overt diabetes with decreased insulin expression and secretion." (PMID 37345014, 2023). "All participants from this study reported they did not have enough money to make ends meet and many were unable to secure basic life-saving medicine such as insulin for diabetes." (PMID 37990313, 2023). "It has been reported that miR-196a2 and miR-27a are involved in the regulation of the insulin signaling pathway and have a strong correlation with diabetes mellitus (DM)." (PMID 37113490, 2023). "It has long been known that administering insulin or insulin secretagogues to treat diabetes has the unfavorable side effect of hypoglycemia." (PMID 38022365, 2023). "Instead, the heterozygous mice were resistant to glucocorticoid- and high-fat diet-induced diabetes and showed improved insulin sensitivity." (PMID 37890668, 2023). "For example, an ML-based system can calculate and provide personalized insulin injection amounts for patients with diabetes or supply personalized smoking cessation messages." (PMID 37647122, 2023). "Less than 1 in 5 (18%) reported stocking insulin and only 14% reported stocking all four types of diabetes products." (PMID 37386440, 2023). "“Diabulimia” and “insulin purging” are terms used to describe the coexistence of AN or AAN with diabetes mellitus." (PMID 38152359, 2023). "Diabetes is a chronic progressive metabolic disease resulting from insufficient insulin production/secretion or insulin resistance." (PMID 37735624, 2023). "The management of diabetes has now entered a new era with new therapeutic molecules, such as gliflozin for patients living with type 2 diabetes, or hybrid insulin delivery systems for patients with insulin-treated diabetes." (PMID 37513978, 2023).
diabetes (continued). "Regular physical exercise is recommended for people with type 1 diabetes mellitus given its beneficial effects on general well-being, cardiometabolic health and insulin requirements." (PMID 36879098, 2023). "Diabetes is a chronic metabolic disease characterized by hyperglycemia, and type 2 diabetes mellitus (T2DM) characterized by insulin dysfunction accounts for the majority (about 95%)." (PMID 38125399, 2023). "Despite the improvement of insulin therapy, hypoglycemia remains the main side effect and is a daily concern for many people with diabetes and their families." (PMID 38089060, 2023). "Diabetes is a chronic medical condition that develops when either the pancreas fails to produce adequate amounts of insulin or the body is unable to use insulin effectively." (PMID 37790676, 2023). "Though hyperglycemia in pediatric patients with diabetes mellitus commonly occurs due to poor adherence to insulin therapy, other etiologies should be considered when hyperglycemia is refractory and additional systemic signs and symptoms are present." (PMID 37012937, 2023). "In Kinshasa, insulin is largely used and there has been a limited range of affordable medications for persons with diabetes." (PMID 38076524, 2023). "Diabetes mellitus is clinically and genetically a heterogeneous group of disorders characterized by dysregulated nutrient metabolism, resulting from defects in insulin secretion and action." (PMID 38149100, 2023). "For the 1403 who developed IAbs (523 of whom developed diabetes), levels of autoantibodies against insulin (IAA), glutamic acid decarboxylase (GADA) and insulinoma-associated antigen-2 (IA-2A) were harmonised for analysis." (PMID 36195673, 2023). "This process is characterized by the ongoing evolution of insulin pump technology, progressively contributing ever more to diabetes care." (PMID 38068755, 2023). "OSA leads to pancreatic β-cell dysfunction, which is manifested by impaired basal insulin secretion and leads to diabetes." (PMID 35257355, 2023). "Ranking these candidates based on CMAP score revealed a number of well-known potentiators of insulin sensitivity including the antioxidant resveratrol, the diabetes medication metformin, and the growth factor FGF21." (PMID 37494090, 2023). "Flow testing was common for devices using positive displacement pumps (e.g., for micro-dose delivery of insulin for diabetes management)." (PMID 37512604, 2023). "With remissions occurring in both types of diabetes, insulin secretion and insulin sensitivity should be thought of as determinants and therapeutic opportunities." (PMID 37409234, 2023). "In conclusion, GLS2 impairment in pancreatic β-cells induces insulin impairment and paradoxical glucagon increase, resulting in diabetes mellitus." (PMID 37147373, 2023). "Patients with diabetes must routinely check their blood glucose levels and often inject insulin if their glucose levels are too much or ingest sweet items if their glucose levels are less." (PMID 36903746, 2023). "Glucose levels in the blood of those with diabetes are higher than usual due to inadequate insulin or cells that are unresponsive to insulin." (PMID 37765971, 2023). "First, the CGM is approved to replace blood glucose monitoring for diabetes management decisions (e.g., guiding insulin doses to correct high-glucose levels), and 97% of participants in this study took advantage of this indication." (PMID 40303243, 2023). "Community pharmacies with more than 50 diabetes patients purchasing insulin and diabetes medicine in a month (for education on diet) and engagement in the training of diabetes were also recognized as facilitators (for compliance monitoring services)." (PMID 37182028, 2023). "Alloxan induces diabetes by damaging the insulin-secreting pancreatic β-cells, resulting in a decrease in endogenous insulin release and a decrease in glucose utilization by the tissues, which leads to hyperglycemia." (PMID 37215365, 2023).